MLKL (mixed lineage kinase domain like pseudokinase)
Diseases named in the same sentence as MLKL in open-access papers (continued):
Sharing a sentence is not in itself a finding about the gene and the disease.
ileitis (6 papers, 2021 to 2025). "Casp8ΔIEC mice are characterized by MLKL mediated epithelial necroptosis, Paneth cell depletion and ileitis." (PMID 34141714, 2021). "Similarly, MLKL deficiency inhibited ileitis caused by the removal of epithelial caspase-8 but only marginally mitigated ileitis in mice deficient in FADD in IECs, implying that MLKL promotes necroptosis or that its deficiency prevents necroptosis." (PMID 39118979, 2024).
Lymphadenopathy (6 papers, 2015 to 2024). Enlargement (swelling) of a lymph node. "The role of caspase-8, RIPK3, and MLKL in non-programmed cell death has been reported to regulate lymphadenopathy, lymphoproliferation and immunodeficiency." (PMID 35064213, 2022).
pneumonia (6 papers, 2018 to 2025). An acute, acute and chronic, or chronic inflammation focally or diffusely affecting the lung parenchyma, caused by an infection in one or both of the lungs (by bacteria, viruses, fungi, or mycoplasma.). "To further elucidate the role of MLKL in murine E. coli pneumonia, we utilized Mlkl-/- mice to confirm the role of neutrophil necroptosis in E. coli-induced pneumonia." (PMID 40359428, 2025). "Immunofluorescence microscopy conducted on lung sections obtained from pneumonia patients displayed more necroptosis, as evidenced by increased phospho-MLKL and RIP-3 expression, compared to that of healthy control lungs." (PMID 30248149, 2018). "Similarly, deletion of MLKL rescued the mice from lethal pneumonia, reduced overall lung injury, decreased the lung bacterial burden, increased neutrophil counts and decreased neutrophil death." (PMID 40359428, 2025). "Note that a direct comparison between WT and MLKL KO mice was not made since we have already demonstrated that MLKL KO mice are protected against severe forms of Spn disease, such as the pneumonia modeled here in our secondary infection." (PMID 31019504, 2019). "PSMs induce the necroptosis of neutrophils through the activation of mixed-spectrum kinase-like protein (MLKL) phosphorylation and increased release of lactate dehydrogenase, which mediates TNF-α secretion via formyl peptide receptor 2 (FPR2) and leads to the exacerbation of pneumonia." (PMID 35878202, 2022).
retinal degeneration (6 papers, 2015 to 2025). Degeneration of the retina. "RIPK/MLKL-mediated necroptosis has been linked to the death of photoreceptors in animal models of retinal degeneration." (PMID 37596046, 2023). "In summary, RIP1 genetic inactivation, or RIP3 and MLKL ablation largely inhibited retinal degeneration induced by IRI." (PMID 39448868, 2025). "Key molecules participating in apoptosis (caspase-3 and caspase-8) and necroptosis (RIP3 and MLKL) were activated in infected mice compared to age-matched, uninfected controls, indicating that both apoptosis and necroptosis participate in retinal degeneration during MCMV latency." (PMID 41012634, 2025).
acute myeloid leukemia (5 papers, 2020 to 2025). Acute myeloid leukemia (AML) is a group of neoplasms arising from precursor cells committed to the myeloid cell-line differentiation. "For example, MLKL induces necroptosis in immunosuppressive tumor-associated macrophages (TAMs) and Mlkl downregulation in acute myeloid leukemia (AML) cells aggravates the disease in mice." (PMID 35422482, 2022). "For example, MLKL acts as a tumor suppressor by increasing endosomal trafficking of granulocyte colony-stimulating factor (G-CSF) in acute myeloid leukemia (AML) cells." (PMID 40070567, 2025). "Here, a reduced level of MLKL correlates to poor survival of patients with acute myeloid leukemia (AML)." (PMID 35422482, 2022). "A recent report identified a non-necroptotic function of MLKL in acute myeloid leukemia (AML) that facilitates the release of G-CSF through MLKL-dependent plasma membrane permeabilization without cell death and hereby promoting cancer cell final differentiation." (PMID 35422482, 2022).
amyotrophic lateral sclerosis (5 papers, 2018 to 2024). Amyotrophic lateral sclerosis (ALS) is a neurodegenerative disease characterized by progressive muscular paralysis reflecting degeneration of motor neurons in the primary motor cortex, corticospinal tracts, brainstem and spinal cord. "Hallmarks of necroptosis including the phosphorylation of RIPK1 and elevated levels of insoluble RIPK1, RIPK3 and MLKL are found in post-mortem human pathological samples such as patients with amyotrophic lateral sclerosis (ALS) and Alzheimer’s disease (AD)." (PMID 34689152, 2021).
cholangiocarcinoma (5 papers, 2021 to 2024). A carcinoma that arises from the intrahepatic biliary tree (intrahepatic cholangiocarcinoma) or from the junction, or adjacent to the junction, of the right and left hepatic ducts (hilar cholangiocarcinoma). "Interestingly, while MLKL expression is typically associated with poor prognosis, studies on cholangiocarcinoma reveal a positive correlation between MLKL-activated necroptosis and favorable immune cell features, including elevated PD-L1 expression." (PMID 39575419, 2024). "Matrine, an alkaloid derived from Sophora flavescens, upregulates RIPK3 expression and promotes MLKL translocation from the cytoplasm to the cell membrane, ultimately inducing necroptosis in cholangiocarcinoma." (PMID 39584140, 2024). "Quercetin and kaempferol, which are natural flavonoids, when used in combination with Smac mimetics, induce the proteasomal degradation of cellular inhibitor of apoptosis proteins one and 2 (cIAP1/2) and synergistically kill cholangiocarcinoma cells through RIPK1/RIPK3/MLKL-mediated necroptosis." (PMID 39584140, 2024). "For instance, researchers have found that gemcitabine could induce RIPK1/RIPK3/MLKL-dependent necroptosis in cholangiocarcinoma cells." (PMID 35756487, 2022).
cholestasis (5 papers, 2016 to 2021). Impairment of the bile flow caused by obstruction within the liver, or outside the liver in the bile duct system. "Increasing evidences suggest that MLKL is involved in pathophysiological conditions, including liver injury, insulin resistance and T2D, cholestasis, and hepatitis 43-46." (PMID 33767595, 2021). "Findings based on BDL of the mouse models suggested a positive correlation between the expression of RIPK3 and MLKL and liver injury; moreover, knockout of RIPK3 could improve cholestasis-related inflammatory necrosis, which was especially effective soon after BDL." (PMID 35432812, 2021).
colon adenocarcinoma (5 papers, 2014 to 2025). "MLKL deficiency in CT26 colon adenocarcinoma (without expression of an artificial antigen such as OVA) also resulted in strongly impaired antitumor activity of combined anti-PD-1/CTLA-4 ICI immunotherapy in tumor-bearing BALB/c mice." (PMID 40345706, 2025). "In human colon adenocarcinoma HT-29 cells, knockdown of RIP1 downstream of MLKL blocked TNF-induced necrosis." (PMID 24932290, 2014).
emphysema (5 papers, 2021 to 2025). "Continued upregulation of RIP3 and p-MLKL and blunted induction of cleaved caspase-3 was found in mice with 6 months’ smoking where emphysema was observed." (PMID 34156033, 2021). "Immunohistochemical staining analysis showed that the expression levels of RIPK1, RIPK3, and MLKL in alveolar epithelial cells in the CS group were higher than those in the normal control group, indicating that necroptosis was enhanced in the lungs of mice with emphysema." (PMID 36979417, 2023).
esophageal cancer (5 papers, 2016 to 2024). A primary or metastatic malignant neoplasm involving the esophagus. "Studies have found that when MLKL phosphorylation levels are elevated, patients with colon and esophageal cancers have poor prognoses and survival outcomes." (PMID 37864090, 2023). "For example, colon and esophageal cancer patients have a poorer prognosis and reduced prognostic survival when MLKL phosphorylation levels are elevated, suggesting that necroptosis promotes tumor progression and migration." (PMID 35965497, 2022).
glioblastoma (5 papers, 2022 to 2025). The most malignant astrocytic tumor (WHO grade IV). "In U251 glioblastoma cells, CRISPR-Cas9-mediated ablation of RIPK1 or MLKL impaired cellular growth, as demonstrated by CCK-8 and colony-formation assays." (PMID 41429922, 2025).
Hepatitis (5 papers, 2016 to 2023). Inflammation of the liver. "MLKL is known to regulate necroptosis during hepatitis through signal transducer and activator of transcription 1 rather than via RIPK3." (PMID 37828052, 2023). "In this model MLKL seems to act as a central player because Mlkl-knockout animals are protected from ConA injury and experimental hepatitis." (PMID 30442947, 2019).
Insulin resistance (5 papers, 2020 to 2025). Increased resistance towards insulin, that is, diminished effectiveness of insulin in reducing blood glucose levels. "Conversely, MLKL activation has been reported to participate in insulin resistance, demyelination, and hepatocellular injury." (PMID 38137900, 2023). "In order to get some clear answers and truly study the contribution of necroptosis, the impact of conditional knockout of MLKL in adult hepatocyte needs be examined in an HFD that induced insulin resistance." (PMID 33353156, 2020). "Whether the endosomal sorting complexes required for transport (ESCRT)-III machinery, which is known to interact with MLKL for exosome formation to dampen pMLKL and promote cell survival, contributes to the development of insulin resistance remains to be determined." (PMID 33353156, 2020).
multiple sclerosis (5 papers, 2020 to 2024). A progressive autoimmune disorder affecting the central nervous system resulting in demyelination. "Caspase-8 activation has been reported to be the key event to determine apoptotic fate of cells, and defective activation of caspase-8 is critical for RIP1/RIP3/MLKL signaling to induce oligodendrocyte necroptosis in multiple sclerosis." (PMID 34725188, 2021). "In support of this theory, MLKL, the protein mediating oligodendrocyte necroptosis in multiple sclerosis as well as the peripheral myelin breakdown after nerve injury, demonstrated an increased expression in the callosal CC1+ cells in Plp-ErbB2V664E mice from 6 dpd." (PMID 34725188, 2021). "However, contraindicating the use of MLKL activating drugs to mitigate neurological disease is the observation that MLKL accelerates demyelination in a necroptosis-independent fashion and thereby worsens multiple sclerosis pathology." (PMID 34071602, 2021). "In the brains of patients with multiple sclerosis, microglia do not undergo necroptosis due to the lower expression of MLKL, whereas oligodendrocytes that have a higher expression of MLKL undergo necroptosis." (PMID 34515928, 2021).
nasopharyngeal carcinoma (5 papers, 2015 to 2025). A carcinoma arising from the nasopharyngeal epithelium. "For example, shikonin, a Chinese herbal medicine extract, can trigger necroptosis in nasopharyngeal carcinoma cells via upregulation of MLKL expression." (PMID 33754026, 2021). "The phosphorylation of MLKL was up-regulated in NA-treated human nasopharyngeal carcinoma C666-1 and HK1 cells." (PMID 25575821, 2015). "Carbon ion was found to induce the expression of MLKL in nasopharyngeal carcinoma." (PMID 34977874, 2021). "Additionally, another study reported that depletion of MLKL severely compromises invasion of the nasopharyngeal carcinoma cells accompanied by the reverse of epithelial-mesenchymal transition (EMT)." (PMID 33754026, 2021). "Of note, MLKL is described to play a role in epithelial-to-mesenchymal transition (EMT) and contribute to the invasive behavior of radioresistant nasopharyngeal carcinoma cells through induction of EMT genes, a function that is suggested to be independent of its phosphorylation status." (PMID 35422482, 2022). "At the same time, high MLKL expression in nasopharyngeal carcinoma has been identified as a negative prognostic marker and knockdown or knockout of MLKL in radioresistant nasopharyngeal carcinoma cells impeded metastasis by suppressing epithelial mesenchymal transition." (PMID 40691738, 2025).
osteosarcoma (5 papers, 2023 to 2024). A usually aggressive malignant bone-forming mesenchymal neoplasm, predominantly affecting adolescents and young adults. "Mechanically, TNFRSF21 upregulated the phosphorylation levels of RIPK1, RIPK3 and MLKL to promote necroptosis in osteosarcoma." (PMID 38184626, 2024). "For necroptosis in osteosarcoma, the formation of the RIP1/RIP3/MLKL complex can induce necroptosis in osteosarcoma cells." (PMID 38800967, 2024). "To test the hypothesis that TNFRSF21 promoted necroptosis in osteosarcoma, we examined the phosphorylation levels of RIPK1, RIPK3 and MLKL." (PMID 38184626, 2024). "Only one cell line, the osteosarcoma cell line STA-et2.1, showed ~10-fold induction of p-MLKL over mock-treated cells, and in three other cell lines, no induction was observed." (PMID 36768641, 2023).
Salmonella Infections (5 papers, 2018 to 2022). Infections with bacteria of the genus SALMONELLA. "Conversely, chimeras in which MLKL was selective deficient in hematopoietic cells (MLKL−/− > WT) were resistant to oral Salmonella infection, as seen by minimal histopathology identical to that observed in control chimeras (WT > WT)." (PMID 29456533, 2018). "Conclusively, these results indicated that MLKL deficiency results in increased intestinal barrier damage following mucosal Salmonella infection." (PMID 29456533, 2018). "MLKL-/- mice are more susceptible to Salmonella infection compared to their wild-type counterparts, with higher mortality rates, increased body weight loss, exacerbated intestinal inflammation, more bacterial colonization, and severe epithelial barrier disruption." (PMID 33050394, 2020). "Besides, mice with MLKL ablation are more susceptible to Salmonella infection and present impaired caspase-1 and GSDMD cleavage with consequently decreased interleukin IL-18 release." (PMID 33050394, 2020). "MLKL−/− mice were more susceptible to Salmonella infection compared with wild-type counterparts, with higher mortality rates, increased body weight loss, exacerbated intestinal inflammation, more bacterial colonization, and severe epithelial barrier disruption." (PMID 29456533, 2018). "This importance is highlighted by the reported finding that RIPK3-MLKL-mediated inflammasome activation is crucial to restraining Salmonella infection in the intestinal mucosa; specifically, MLKL-/- mice show impaired caspase-1 cleavage and pathogen clearance." (PMID 36127465, 2022). "A recent study also identified activation of caspase-1 and GSDMD (pyroptosis), caspase-8, caspase-7, and caspase-3 (apoptosis), and mixed lineage kinase domain-like pseudokinase (MLKL) (necroptosis) during Salmonella infection." (PMID 33494299, 2021). "As intercellular junctions are crucial for epithelial barrier function, we wondered if Salmonella infection also induced any changes in tight junctions between WT mice and MLKL−/− mice." (PMID 29456533, 2018). "Mucin 2, the major component of the mucus layer, also trended to decrease in MLKL−/− mice following Salmonella infection." (PMID 29456533, 2018). "To determine in which cell populations MLKL expression mediated protective effects against Salmonella infection, we generated bone marrow chimeras." (PMID 29456533, 2018). "On day 8 p.i., we observed that all of MLKL−/− mice had died, whereas almost 66.7% of WT mice remained alive, and the entire cohort of WT mice succumbed to Salmonella infection within 15 days." (PMID 29456533, 2018). "In the current study, we showed that MLKL plays a critical role in intestinal defense against Salmonella infection and MLKL-mediated inflammasome activation in the epithelial compartment limits early bacterial mucosal colonization." (PMID 29456533, 2018). "Moreover, MLKL protects from Salmonella infection promoting intestinal epithelial barrier function by inducing inflammasome activation in IECs." (PMID 33050394, 2020). "However, mucin expressions were dramatically reduced in MLKL−/− mice following Salmonella infection." (PMID 29456533, 2018). "Moreover, MLKL expression in non-hematopoietic cells had a critical role in protection during Salmonella infection, as evidenced by WT and MLKL−/− chimeric mice." (PMID 29456533, 2018).
Splenomegaly (5 papers, 2021 to 2024). Abnormal increased size of the spleen. "Although Abin1Q478H/Q478H cells are sensitive to RIPK1 kinase–RIPK3–MLKL‐dependent necroptosis, only anemia and splenomegaly are alleviated by RIPK3 deficiency but not by MLKL deficiency or the RIPK1 kinase‐dead mutation." (PMID 38009796, 2024). "Therefore, persistent inflammation (splenomegaly) during leptospirosis is a result of a large chemo-cytokine release in the system and necroptosis activation (induction of MLKL/RIP3) which can further lead to membrane pore formation leading to cell death." (PMID 35392072, 2022).
Ureteral obstruction (5 papers, 2019 to 2025). Obstruction of the flow of urine through the ureter. "Unilateral ureteral obstruction (UUO) in the neonatal mouse caused renal structural injury, induced key molecules of the necrosome (RIPK3 and phospho-MLKL) and generated inflammatory cytokines (IL-1α, INF-γ and TNF-α) in the neonatal kidney." (PMID 31819111, 2019).
bronchiolitis (4 papers, 2020 to 2022). Inflammation of the bronchioles characterized by swelling of the bronchioles and mucus accumulation. "Significantly, the inhibition of MLKL or RIPK1 decreased RSV-induced hAEC cell death and associated HMGB1 release in vitro, and conferred protection against severe bronchiolitis in vivo in a preclinical model." (PMID 35712662, 2022). "Further studies are needed to determine whether MLKL is a tractable therapeutic target to reduce the severity of viral bronchiolitis, irrespective of whether epithelial cell death contributes to the underlying endotype driving disease pathogenesis." (PMID 35712662, 2022).